BRCA1 (BRCA1 DNA repair associated)
Diseases named in the same sentence as BRCA1 in open-access papers (continued):
Sharing a sentence is not in itself a finding about the gene and the disease.
breast cancer (continued). "Mutations in the BRCA gene, BRCA1 and BRCA2 is the most common germline aberrations associated with breast cancer having a collective 70% lifetime risk of developing breast cancer." (PMID 36185256, 2022). "The high mobility group A1 (HMGA1), a chromatin regulator, had been shown to suppress BRCA1 gene expression in human breast cancer." (PMID 36338996, 2022). "The mean age of patients who carried deleterious variant in BRCA1/BRCA2 was 39 years and 8 months compared to 47 years and 3 months among women who carried a deleterious variants in other breast cancer susceptibility genes." (PMID 35039564, 2022). "Pathogenic variants and germline mutations in BRCA1 and BRCA2 can increase the risk of developing breast cancer at a younger age, as these mutations represent more than 50% of all mutations in breast cancer-related genes in young women of specific populations." (PMID 36685821, 2022). "This study examines BRCA1/2 testing rates among women aged ≤45 years with breast cancer in Massachusetts in 2010–2013 using linkage between the state's cancer registry and All‐Payer Claims Data." (PMID 35312162, 2022). "BRCA1 and BRCA2 gene mutations are responsible for 5% of breast cancer (BC) and 10–15% of ovarian cancer (EOC)." (PMID 36307994, 2022). "This was further investigated by examining the promoter methylation status of BRCA1 in breast cancers with CN17 attribution." (PMID 35705804, 2022). "Prompted by these observations in mouse models and prior studies showing enhanced expression of TGFβR2 in CSC-enriched BLBC cells, we examined the relationship between BRCA1 with TGFβR2 mRNA levels in human breast cancer sample sets." (PMID 35236825, 2022). "Recent studies have revealed that the BRCA1 c.5339T>C; p.Leu1780Pro (L1780P) missense mutation in the BRCT domain is closely associated with breast cancer in Korean patients." (PMID 35626017, 2022). "Taken together, we identified a synthetic lethal interaction between EZH2 and ATM and propose this synergistic interaction as a novel molecular combination for the treatment of BRCA1-mutant breast cancer." (PMID 35715861, 2022). "Pathogenic germline variants (PGVs) in one of the known high-risk breast cancer susceptibility genes e.g. BRCA1, BRCA2, PALB2 confer a high risk of developing breast cancer and are enriched in familial cases." (PMID 33763779, 2022). "Meanwhile, the MEDIOLA trial showed that a combination of PARPi and anti-PD-L1 led to enhanced antitumor activity in one of the four cohorts for patients with advanced-stage BRCA1/2-mutant breast cancers." (PMID 36359297, 2022). "These novel metabolic effects of BRCA1 are a potential mechanism by which it inhibits breast cancer." (PMID 36193432, 2022). "High expression levels of RING domain-deficient BRCA1 proteins promote cisplatin and PARPI resistance by reducing the DNA repair capacity of BRCA1 in breast cancer cell lines." (PMID 35785170, 2022). "In population studies unselected for family history, 4–33% of male breast cancer patients harbor BRCA2 mutations and 0–6% harbor BRCA1 mutations." (PMID 35656339, 2022). "Here, we assessed the associations of the newly developed 313-SNP breast cancer PRS and 147-SNP prostate cancer PRS derived using population-based data, with breast and prostate cancer risks, respectively, for male BRCA1 and BRCA2 carriers." (PMID 34320204, 2022).
breast cancer (continued). "The absence of an association of LBC with BRCA1 has already been noted by ourselves and others, with only 2/342 (0.58%) LBCs in BRCA1 breast cancer patients in one study." (PMID 33763779, 2022). "Mutations in the BRCA1 gene are associated with triple-negative cancer and in the BRCA2 gene for estrogen receptor-expressed breast cancer." (PMID 35626173, 2022). "Breast cancers from BRCA1 PV carriers expressed significantly lower ER (15.2% vs 78.2%, p < 0.001) and lower PR (6.8% vs 41.1%, p < 0.001) staining compared to non-PV carriers." (PMID 35135604, 2022). "In summary, we provide evidence that HspBP1 plays an important role in preventing tumorigenesis in BRCA1-proficient breast cancer." (PMID 35387978, 2022). "In our cohort there was an equal proportion of women who carried a deleterious variant in BRCA1/BRCA2 (1.8%) and women who carried a deleterious variant in other breast cancer susceptibility genes (1.8%)." (PMID 35039564, 2022). "An important master gene regulator in breast cancer, such as BRCA1, activates the Notch pathway in breast cancer cells through transcriptional upregulation of Notch receptors and ligands." (PMID 35205721, 2022). "A subsequent study employing 456 breast cancer patients of varying subtypes validated that, in addition to BRCA1/2 status, high degrees of LST were correlated to RAD51C mutational status." (PMID 36077694, 2022). "Patients older than 18 years, with a deleterious germline BRCA1/2 (gBRCA1/2) mutated, metastatic, or locally advanced and HER2-positive breast cancer were enrolled." (PMID 36045677, 2022). "In recent studies of BRCA1/2 screening in unselected breast cancer cases, the ratio was closer to 50%." (PMID 35158866, 2022). "At this threshold, studies of breast cancer using GWAS have missed the association of BRCA1 and BRCA2 (prevalences <<1%), even though they are associated with a lifetime risk of breast cancer in women of 65% and 45%, respectively." (PMID 35275946, 2022). "Further supporting this idea is the finding that genetic variations in HMMR27 modify breast cancer risk in BRCA1 mutation carriers and DYNLL1 expression correlates with survival in BRCA1-mutant patients that develop ovarian cancer." (PMID 35459234, 2022). "The aim of our mini-review is to summarize state of art knowledge on pregnancy after breast cancer in BRCA1/2 carriers." (PMID 35062994, 2022). "PRS interactions with age and BRCA1 and BRCA2 pathogenic variant characteristics for BRCA1 and BRCA2 carriers with breast cancer risk and prostate cancer risk." (PMID 34320204, 2022). "Collectively, our findings confirm the presence of BRCA1/2 and other DDR gene alterations in a substantial proportion of the Chinese breast cancer population and demonstrate their association with poor patient outcomes." (PMID 35494038, 2022). "The results showed that BRCA1/2 were overexpressed in breast cancer as compared to their expression levels in normal tissues." (PMID 35409110, 2022). "The reversion mutations occurred only in 3 out of the 15 HRR genes: BRCA1 (3.8%), BRCA2 (3.5%) and PALB2 (2.0%) from 11 patients (6 breast cancers, 1 ovarian cancer, 1 pancreatic cancer, 1 lung cancer and 2 breast and ovarian dual cancers)." (PMID 35281878, 2022). "The absolute risks to age 80 years ranged from 0.4% for male breast cancer to approximately 2.5% for pancreatic cancer for BRCA1 carriers and from approximately 2.5% for pancreatic cancer to 27% for prostate cancer for BRCA2 carriers." (PMID 35077220, 2022).
breast cancer (continued). "There was a negligible increase in survival in almost all carriers of the pathogenic variants of BRCA1 and BRCA2 with TN breast cancer in stage II who underwent any secondary risk–reducing strategy compared with surveillance." (PMID 36580360, 2022). "In females, BRCA1 and BRCA2 alterations lead to a 72% and 69% cumulative lifetime risk of breast cancer, respectively, and a cumulative lifetime risk of ovarian cancer of 44% and 17%, respectively." (PMID 35933387, 2022). "Population-based prostate and female breast cancer PRS are associated with a wide range of absolute breast and prostate cancer risks for male BRCA1 and BRCA2 carriers." (PMID 34320204, 2022). "Socioeconomic and racial/ethnic disparities exist in BRCA1/2 testing among women with breast cancer in Massachusetts, despite equitable insurance coverage of testing." (PMID 35312162, 2022). "Germline mutations in both the BRCA1 and BRCA2 genes are found in hereditary breast and ovarian cancers and account for around 7% of breast cancers with a predisposition toward TNBC status." (PMID 35884530, 2022). "In the case of ovarian and breast cancers, we limited our study to the subset of patients with available data for the methylation status of the BRCA1/RAD51C promoter." (PMID 35783256, 2022). "In basal-like and BRCA1-related breast cancers, ROS expression was correlated with AhR levels and the expression of the chemokines CXCL1, CXCL2, and CCL5." (PMID 36588678, 2022). "Multiple pathogenic variants of the BRCA1 and BRCA2 genes that confer high relative risks of breast cancer have been identified." (PMID 35395775, 2022). "At this point, breast cancer 1 (BRCA1), breast cancer 2 (BRCA2), and partner and localizer of BRCA2 (PALB2) proteins interact to promote RAD51 filament assembly and stimulate strand invasion." (PMID 35163621, 2022). "In a recent study, Cur was shown to suppress the proliferation of breast cancer cell lines and increase the mRNA and protein levels of the Brca1 by reducing promoter methylation." (PMID 35327559, 2022). "Multiple breast cancer cluster regions (BCCR) and ovarian cancer cluster regions (OCCR) have been observed in BRCA1 and BRCA2 and are associated with relatively elevated breast cancer risk and lower ovarian cancer risk or inversely." (PMID 35469032, 2022). "In contrast, a transient increase in choline compounds was observed in Breast Cancer gene 1, BRCA-1 mouse mammary tumors sensitive to docetaxel treatment." (PMID 35250970, 2022). "The BRCA1 gene suppressed basal stem cell expansion during mammary tumor development and downregulated MYC expression, quenching the MYC-driven oncogenic pathways." (PMID 36207293, 2022). "So, the presence of PARP1 inhibits the functioning of HR, causing mutations in BRAC proteins, and from various studies, it was found that ≈70% of mutated BRCA1 and ≈16–23% of mutated BRCA2 breast cancers are regarded as TNBCs." (PMID 35631368, 2022). "The ability of PRSER+ to discriminate between controls and breast cancer cases was estimated as an AUC of 0.60 (95% CI = 0.51 to 0.69) for BRCA1 and 0.59 (95% CI = 0.55 to 0.63) for BRCA2 carriers." (PMID 34320204, 2022). "To identify metastatic suppressors, we used Brca1-mutant (Brca1-MT) 545 cells, which were isolated from a primary mammary tumor of a Brca1-MSK mouse." (PMID 35025764, 2022). "A similar percentage of 90% occurred for BRCA1 breast cancers but was less evident (54%) for BRCA2 breast cancers." (PMID 35039532, 2022). "The BRCA1 c.4524G > A p.(Trp1508Ter) variant was identified in BRB130, a Tswana-speaking woman diagnosed with breast cancer at age 45 years and 8 months." (PMID 35039564, 2022). "Although we investigated the correlation between BRCA1/2 and breast cancer patients, some limitations remain." (PMID 35409110, 2022).
breast cancer (continued). "Based on the same principle described in the breast cancer section above, three PARP inhibitors (olaparib, rucaparib, and niraparib) were approved as maintenance therapies for BRCA1/2-mutated ovarian cancer." (PMID 36209184, 2022). "Germline defective BRCA1 is a known strong driver for the ER-/PR- breast cancer, and approximately 80% are ER−/PR− in women carrying BRCA1 PVs." (PMID 35135604, 2022). "The precision obtained for Intrahepatic cholangiocarcinoma was 0.85 and for Non BRCA1/BRCA2 familial breast cancer was 0.89." (PMID 36401182, 2022). "As a result, the mutation of BRCA1 results in EMT being induced, which promotes metastasis of breast cancer cells." (PMID 35740092, 2022). "For example, less than 25% of breast cancer inheritance is due to known high-penetrance genes (including BRCA1 and BRCA2)." (PMID 36171609, 2022). "Somatic tandem duplications (TDs) are commonly found in breast cancer and ovarian cancer that show failure of homologous recombination (HR) repair of DNA double-strand breaks, for example, owing to defective BRCA1 or BRCA2 expression." (PMID 35705804, 2022). "In the present study, we found that HspBP1 suppresses breast cancer tumorigenesis and promotes HR-mediated DNA repair, and these effects depend on BRCA1." (PMID 35387978, 2022). "Nonetheless, BRCA1 breast cancers have obvious edge enhancement, which enables excluding fibroadenoma diagnosis." (PMID 35402620, 2022). "Previous results from our group showed that PRMT5 inhibition in breast cancer cells can promote the m6A modification of BRCA1 mRNA and reduce its stability." (PMID 35563196, 2022). "For our exemplar clinical scenario, we applied this pathway to BRCA-testing (BRCA1/BRCA2/PALB2 gene testing) in unselected mainstream patients with breast cancer." (PMID 35868849, 2022). "The mean age of patients who carried deleterious variant in BRCA1/BRCA2 was 39 years and 8 months compared to 47 years and 3 months among women who carried a deleterious variant in other breast cancer susceptibility genes." (PMID 35039564, 2022). "In a The Cancer Genome Atlas (TCGA) cohort of 467 breast cancer patients, a significant association between the degree of LST and BRCA1/2 and RAD51C mutational status or expression levels was also found." (PMID 36077694, 2022). "This phase II study met its primary endpoint and showed activity of lurbinectedin in germline BRCA1/2 breast cancer." (PMID 36037567, 2022). "This study confirmed previous known patterns, including that ER-/PR- breast cancers are more often seen in BRCA1 PV carriers, in younger females, whereas ER + /PR + breast cancers are more often seen in BRCA2 PV carriers." (PMID 35135604, 2022). "Testing for PIK3CA mutation, germline BRCA1/2, PALB2 pathologic variant, homologous recombination deficiency (HRD), PD-L1 expression, and TMB is some of the latest developments to guide breast cancer treatment." (PMID 35884530, 2022). "We discovered that heterozygous germline deletion, or epithelia-specific deletion of Brca1 in mice, activates Tgfβr2 signaling pathways in mammary tumors." (PMID 35236825, 2022). "Both of the rare variants that we identified in these well-established colon (APC) and breast cancer (BRCA1) genes would likely be missed by imputation, subject to the reference population used." (PMID 35314819, 2022). "The impact of RRBSO in patients with BRCA1 and BRCA2 mutation with TN breast cancer in stage I/II increased with age." (PMID 36580360, 2022). "This phase II basket multitumor trial (NCT02454972) evaluated lurbinectedin 3.2 mg/m2 1-h intravenous infusion every 3 weeks in a cohort of 21 patients with pretreated germline BRCA1/2 breast cancer." (PMID 36037567, 2022).
breast cancer (continued). "Circ_0043947 (393 nt) was generated from the back-splicing of exon 18–23 of its host gene breast cancer 1, early onset (BRCA1)." (PMID 35331286, 2022). "For example, UBE2T promoted the proliferation of breast cancer cells via ubiquitinating and downregulating BRCA1." (PMID 35169125, 2022). "Down-regulation of miR-218 was observed in cisplatin-resistant breast cancer cell lines and it was identified that BRCA1 was the cellular target of miR-218." (PMID 35328651, 2022). "BRCA1, a RING-containing tumor suppressor E3 ligase and implicated in breast cancers, forms a heterodimeric RING complex with BARD1 in the nucleus of cells." (PMID 35327659, 2022). "We then tested the interaction between HspBP1 and BRCA1 in BRCA1 mutant breast cancer cell line HCC1937 and its derivative cell line reconstituted with wild type BRCA1 (HCC1937-BRCA1)." (PMID 35387978, 2022). "Protein truncating variants in ATM, BRCA1, BRCA2, CHEK2, and PALB2 are associated with increased breast cancer risk, but risks associated with missense variants in these genes are uncertain." (PMID 35585550, 2022). "Survival analysis using a cure model indicated that patients of early ER+ breast cancers with high BRCA1 expression developed rapid distant metastasis." (PMID 34996912, 2022). "Patients with BRCA1-mutant breast cancer and high EZH2 expression showed an improved therapeutic response and less frequent disease recurrence after treatment with intensified platinum-based chemotherapy, compared to standard chemotherapy." (PMID 35715861, 2022). "BRCA1 and BRCA2 germline pathogenic variants (GPVs) account for most of the 5-10% of breast cancer (BC) that is attributable to inherited genetic variants." (PMID 36119527, 2022). "The objective of this study is to search for mutations in the BRCA1 (c.5177_5180delGAAA and c.4986+6T>C) and BRCA2 genes (c.6445_6446delAT) in a population of women diagnosed with breast cancer." (PMID 35950060, 2022). "Approximately 75% of breast cancers containing germline mutations in BRCA genes (gBRCA) show a triple negative phenotype, with BRCA1 dysfunction frequently being one of the main drivers." (PMID 36085046, 2022). "Women at risk for these persisting major concerns are aged below 35 (BRCA1) or 40 (BRCA2) years, unemployed, lower educated, have a history of breast cancer or a more recent BRCA1/2-PV diagnosis." (PMID 34997316, 2022). "This review summarizes the impact of different cytotoxic agents on a fertility, fertility preservation, maternal and fetal prognosis after pregnancy in breast cancer survivors with BRCA1/2." (PMID 35062994, 2022). "This was found by using genetic markers to test for BRCA1 and BRCA2 mutations in families from the Breast Cancer Linkage Consortium (BCLC)." (PMID 35740092, 2022). "These novel metabolic findings represent a potential mechanism by which BRCA1 exerts its inhibitory effect on breast cancer." (PMID 36193432, 2022). "Mutations in two genes known as breast cancer (BRCA) genes, BRCA1 and BRCA2, are linked with 5 to 10% of all breast cancers." (PMID 36421343, 2022). "It is therefore unlikely that failure to test those with known BRCA1/2 PVs missed PVs in other breast cancer genes." (PMID 33758026, 2022). "Further, it has been revealed that BRCA1-related tumors profile resembles the TNBC subtype, while the profile of the BRCA2-associated tumor correlates to luminal-like breast cancers, particularly the Luminal B subtype." (PMID 35145999, 2022). "Patients with positive expression of the BRCA1 and BRCA2 genes have about an 80% risk of developing breast cancer later in life, mainly around pre-menopausal age." (PMID 35950060, 2022). "In ultrasound examination, BRCA1 and BRCA2-mutated breast cancer demonstrates an irregular shape and blurred boundary hypoechoic masses." (PMID 35402620, 2022). "In breast cancer, concomitant administration of a CHK1 inhibitor and olaparib restored the sensitivity of BRCA1-deficient resistant triple negative breast cancer (TNBC) cells." (PMID 36091750, 2022).